AKT1 (AKT serine/threonine kinase 1)
Diseases named in the same sentence as AKT1 in open-access papers (continued):
Sharing a sentence is not in itself a finding about the gene and the disease.
keloid (13 papers, 2015 to 2025). An irregularly shaped, elevated mark on the skin caused by deposits of excessive amounts of collagen during wound healing. "The mRNA levels of Akt1 and mTOR in keloid fibroblasts from the IGF-1+Wubeizi ointment-treated group was higher than those in keloid fibroblasts from the Wubeizi ointment-treated group (P < 0.05)." (PMID 33062677, 2020). "The results of qPCR showed that, compared to the control group, mRNA levels of PIK3CA, Akt1, and mTOR were significantly increased in keloid fibroblasts from the IGF-1-treated group (P < 0.05)." (PMID 33062677, 2020). "In contrast, compared to the control group, mRNA levels of Akt1 and mTOR were significantly decreased in keloid fibroblasts from the IGF-1+Wubeizi ointment-treated group and Wubeizi ointment-treated group (P < 0.05)." (PMID 33062677, 2020). "AKT1, the fourth Wnt-gene paired to RP11-91I11.1, did not significantly change in keloids by intracellular qPCR and therefore did not pass the validation." (PMID 28404955, 2017).
lymph node metastasis (13 papers, 2010 to 2025). "High expression levels of AKT1 was associated with lymph node metastasis (p = 0.033)." (PMID 34531452, 2021). "Kaplan–Meier plots showed that high expression of Akt1 and low expression of mir-637 are highly correlated with poor prognosis in patients with lymph node metastasis of TNBC." (PMID 33911067, 2021). "When comparing gene expression levels in all cases with and without lymph node metastasis, we found that high levels of AKT1 were associated with the presence of lymph node metastasis." (PMID 34531452, 2021). "However, women with/without AKT1 mutations were similar in terms of age, tumor size, lymph node metastasis, and Ki67 score." (PMID 34093841, 2021). "Moreover, it was stated that the expression level of the PIK3CA, PIK3R1, PTEN, AKT1, mTOR genes does not depend on the patients’ age, lymph node metastases, ER, PR status and Ki-67 index." (PMID 33669698, 2021).
malignant glioma (13 papers, 2007 to 2023). A grade III or grade IV glioma arising from the central nervous system.
periodontitis (13 papers, 2020 to 2025). An acute or chronic inflammatory process that affects the tissues that surround and support the teeth. "It is predicted that PTGS2 and BCL2 are the most important targets of the Asarum–Angelica drug pair for regulating periodontitis, and AKT1, CASP3, BAX, RELA, etc., are also relatively important targets." (PMID 38139216, 2023). "It was discovered through network graph analysis that targets such as PTGS2, BCL2, AKT1, and CASP3 are the main targets of the Asarum–Angelica drug pair in the treatment of periodontitis." (PMID 38139216, 2023). "The molecular docking results showed that BBR can effectively bind to periodontitis targets ALOX5, AKT1, NOS2, and TNF, indicating that these four targets have high biological activity and can serve as potential biomarkers and key therapeutic targets for BBR treatment of periodontitis." (PMID 38704553, 2024).
prostate adenocarcinoma (13 papers, 2019 to 2025). "Exome sequencing by the Broad/Cornell group on the human prostate adenocarcinoma showed only 15% of the patients with genetic alterations in the PI3K/Akt pathway, out of which 7% alterations were in PTEN and a single case of missense mutations was observed in Akt1 and Akt3 isoforms." (PMID 31360736, 2019). "In addition, the knockdown of AKT1 and AKT2 reduced lactate production in the prostatic adenocarcinoma cell line PC3." (PMID 38396845, 2024). "Data from the RNA-seq analysis indicated no significant gain or amplification of Akt1 mRNA in these prostate adenocarcinoma samples." (PMID 31360736, 2019).
type 1 diabetes (13 papers, 2013 to 2025). "By using an experimental type 1 diabetes mouse model, it has been demonstrated that HMGB1 maintains inflammation via modulation of RAGE/AKT1/β-catenin signaling pathway in the diabetic lung." (PMID 34008469, 2021).
vitiligo (13 papers, 2014 to 2025). Generalized well circumscribed patches of leukoderma that are generally distributed over symmetric body locations and is due to autoimmune destruction of melanocytes. "In patients with vitiligo, Akt1 phosphorylation is reduced and impaired PI3K/Akt activation is involved in keratinocyte apoptosis." (PMID 24410795, 2014). "While current literature on the direct impact of Kaempferol on mitochondrial function is limited, the implication of interaction with AKT1 indicates a potential pathway where Kaempferol could improve vitiligo by modulating mitochondrial and cell apoptosis." (PMID 38659590, 2024). "The five key target genes (AKT1, VEGFA, ESR1, IL2, and MPO) identified by the compound–target network were closely related to the pathogenesis and/or treatment of vitiligo." (PMID 38659590, 2024). "Based on the results of network pharmacology, molecular docking was performed to validate the binding modes of the top three active components (i.e., luteolin, quercetin, wogonin) and the top three FHB-vitiligo targets (i.e., RELA, STAT3, AKT1)." (PMID 37575231, 2023). "The hub genes of vitiligo melanocytes include CDK1, HSP90AA1, AKT1, BCL2L1, HDAC2, HELLS, and KIF23." (PMID 33790887, 2021). "In addition, network pharmacology analysis identified AKT1, RELA, and STAT3 as key targets of FHB for vitiligo treatment." (PMID 37575231, 2023).
clear cell renal cell carcinoma (12 papers, 2014 to 2026). "Except for Akt missense mutations, activating AKT1/2 indels are detected in breast, prostate and clear-cell renal cancers." (PMID 34419139, 2021). "Graphs according to 58 clear cell renal cell carcinoma tissues regarding AKT1 expression intensity and proportion results obtained by immunohistochemistry are shown." (PMID 36286049, 2022). "Then, we analyzed how AKT1 alteration affects clear cell renal cell carcinoma." (PMID 36286049, 2022).
Huntington disease (12 papers, 2014 to 2026). Huntington disease (HD) is a rare neurodegenerative disorder of the central nervous system characterized by unwanted choreatic movements, behavioral and psychiatric disturbances and dementia. "In particular, Huntington’s disease signaling, T cell activation, Apoptosis and survival signaling were the most significantly enriched pathways in both SALS patient subgroups, with AKT1, NFKB1 and SOS as the major key involved genes." (PMID 31292500, 2019). "The results showed that AKT1 mainly involves 12 pathways, with the most significant being ubiquitin-mediated proteolysis; DRD4 mainly involves 7 pathways, with the most significant being AA metabolism; KMO mainly involves 4 pathways, with the most significant being Huntington disease." (PMID 39312335, 2024).
inflammatory bowel disease (12 papers, 2017 to 2025). A spectrum of small and large bowel inflammatory diseases of unknown etiology. "The RELA protein is treated as a potential cancer biomarker, responsible for cytokine production and inflammatory bowel disease, when AKT1 is a protein that aids in the correct growth and operation of the nervous system." (PMID 37993790, 2023). "AKT1 ablation promoted the polarization of macrophage M1, which could affect the severity of inflammatory diseases, such as inflammatory bowel disease, and was related to the regulation of innate immunity and inflammation." (PMID 35586697, 2022).
mesothelioma (12 papers, 2014 to 2025). A usually malignant and aggressive neoplasm of the mesothelium which is often associated with exposure to asbestos. "Both PI3K genes, PIK3CA and PIK3CD, all 3 AKT genes, AKT1, AKT2 and AKT3, as well as BCL2 gene were detected in mesothelium and mesothelioma samples." (PMID 32664372, 2020). "Furthermore, lower expression of CDK7, AKT1, PARP1 (p < 0.1), CCND2 (cyclin D2), CDK2, CDK4, BIRC5 (survivin), PCNA and CDH2 (N-cadherin) (p < 0.005) have been shown to result in longer median survival of patients with mesothelioma." (PMID 36304150, 2022).
rectal cancer (12 papers, 2011 to 2025). A primary or metastatic malignant neoplasm that affects the rectum. "It seems that AKT1 plays crucial role in transition of grade II rectum cancer into grade II." (PMID 30774817, 2018). "In conclusion it seems that AKT1, EGFR, and TP3 are suitable drug targets to prevent rectum cancer progression." (PMID 30774817, 2018). "It seems that AKT1, EGFR, and TP3 are suitable drug targets to prevent rectum cancer progression." (PMID 30774817, 2018).
T cell lymphoma (12 papers, 2011 to 2025). "In the model system generated by Kharas and colleagues using a myristoylated Akt1, recipients develop myeloproliferative disease, T-cell lymphoma or AML." (PMID 21998731, 2011). "Computational analysis identified key T-cell lymphoma targets, with molecular docking suggesting DMBP’s anticancer properties through interactions with proteins like AKT1 and mTOR." (PMID 40699833, 2025).
thyroid (12 papers, 2014 to 2025).
adenoma (11 papers, 2015 to 2025). A neoplasm arising from the epithelium. "As a result of K-means clustering, the expression levels of five genes, AKT1, BCL2L1, ERBB2, MTA2 and TNFRSF25, were found to be significantly up-regulated (p < 0.05) in LST-adenoma, compared to Ip-adenoma." (PMID 26048755, 2015). "By K-means clustering, the expression levels of five genes, AKT1, BCL2L1, ERBB2, MTA2 and TNFRSF25, were seen to be significantly up-regulated (p <0.05) in LST-adenoma compared to Ip-adenoma." (PMID 26048755, 2015).
B-cell lymphoma (11 papers, 2014 to 2024). "Our work displayed that QHF has 541 significant targets in B cell lymphoma, among which MAPK1/ERK2 and AKT1 are mostly enriched." (PMID 35818037, 2022).
chondrosarcoma (11 papers, 2016 to 2024). A malignant cartilaginous matrix-producing mesenchymal neoplasm arising from the bone and soft tissue. "In order to investigate whether the PI3K/Akt pathway is regulated in visfatin-induced promotion of PDGF-C expression, we treated chondrosarcoma cells with Ly294002 or wortmannin (PI3K inhibitors), an Akt1/2 inhibitor, or transfected the cells with the respective siRNAs." (PMID 36359873, 2022).
Hypoglycemia (11 papers, 2014 to 2025). A decreased concentration of glucose in the blood. "Meanwhile, morusin, kuwanon C and morusyunnansin L are probably the important ingredients of MLF in hypoglycemia, which may function by regulating key targets, including ADORA1, AKT serine/threonine kinase 1 (AKT1), PPARγ and glycogen synthase kinase-3 beta (GSK3β)." (PMID 36278175, 2022).
liver diseases (11 papers, 2014 to 2025). "It has been reported that AKT1 was associated with inflammation of liver disease and acute pancreatitis." (PMID 32047813, 2020). "This indicated AKT1 was a vital target to BWG treating liver disease, which was corresponded to the MCODE clustering result previous." (PMID 40217538, 2025). "AKT1 on the other hand is the topmost interactive gene that plays an important role in the PI3K/AKT signaling pathway, cell cycling, cell migration, proliferation, focal adhesion, mitochondrial function, and collagen secretion in liver diseases." (PMID 40025530, 2025).
prostate intraepithelial neoplasia (11 papers, 2006 to 2025). A neoplastic proliferation of the epithelial cells that line the acini and the ducts of the prostate gland. "In contrast, PTEN-deficient tumors and AKT1-induced prostate intraepithelial neoplasia are sensitive to inhibition of mTOR, which is a downstream effector of the PI3K/AKT pathway." (PMID 19517027, 2008). "Treatment with rapalogs also reversed Akt-induced prostatic intraepithelial neoplasia (PIN) phenotype in the model of transgenic mice expressing human AKT1 in the ventral prostate (AKT1-Tg)." (PMID 32341756, 2020).
thyroid tumor (11 papers, 2009 to 2025). A benign or malignant neoplasm affecting the thyroid gland. "Akt1 or Akt2 ablation prevents thyroid tumour onset in Pten+/− mice." (PMID 28082369, 2017). "Studies with human thyroid tumors have suggested that the invasion and metastasis of FTC, as activated by this pathway, mainly affect activation and nuclear localization of Akt1, which coincides with the presence of Akt1 mutations in the metastatic thyroid cancers." (PMID 31109060, 2019).
Cachexia (10 papers, 2014 to 2025). Severe weight loss, wasting of muscle, loss of appetite, and general debility related to a chronic disease. "Remarkably, we observed similar results in the validation cohort of patients, showing that individuals who carry the AKT1-rs1130233-GG genotype or the C-allele of the SELP-rs6136 polymorphism were at reduced risk of developing cachexia." (PMID 25238546, 2014). "The association of SELP-rs6136, IL6-rs1800796 and AKT1-rs1130233 polymorphisms with cachexia as well as the correlation between cachexia and the candidate polymorphisms and overall survival were analyzed." (PMID 25238546, 2014). "Conversely, a correlation was observed between the AKT1-rs1130233 genotype and cachexia, with significantly higher proportion of patients harboring at least one A-allele having cachexia (i.e. 37 out of 81, versus 16 out of 70 GG patients, p = 0.004)." (PMID 25238546, 2014). "Among the upregulated genes, Il6ra, Cdkn1a, Csf2rb2, and Akt1, and among the downregulated genes, Col1a1 and other collagen-related genes were involved in multiple pathways, suggesting their key function in cachexia." (PMID 34175899, 2021). "Therefore, we examined the effects of an inhibitor of AKT1 (siRNA) in the cancer cachexia models, and found that the expression of the Akt/FOXO3a signaling pathways had changed, with higher expression of MaFbx." (PMID 34724970, 2021). "To investigate whether there is an association between cachexia and IL6-rs1800796, AKT1-rs1130233 and SELP-rs6136 polymorphisms, we performed genotyping using genomic DNA extracted from peripheral blood samples." (PMID 25238546, 2014). "Therefore in the present study we evaluated the association of these candidate polymorphisms in the AKT1, IL6, and SELP genes with cachexia in a total population of 303 PDAC patients, in two independent cohorts." (PMID 25238546, 2014). "Therefore, in the current study we investigated the association with cachexia and the prognostic value of the candidate functional polymorphisms IL6-rs1800796, AKT1-rs1130233 and SELP-rs6136 in a first cohort of 151 patients with locally-advanced or metastatic PDAC." (PMID 25238546, 2014).
cytomegalovirus infection (10 papers, 2020 to 2024). A herpesvirus infection caused by Cytomegalovirus. "Similarly, hsa-miR-199a-3p and hsa-miR-613 were found downregulated in HCMV infection targeting AKT1 and ARG2 genes, respectively." (PMID 36159991, 2022). "The most important protein targets based on its degree from the C-T-P-D network were TNF, MAPK1, MAPK3, IL6, IL1B, AKT1 and CASP3 and the most important pathways associated with these protein targets were “Pathways in cancer”, “IL-17 signaling pathway”, and “Human cytomegalovirus infection”." (PMID 36591238, 2022). "On the other hand, eight out of ten anti-COVID-19 core targets (TNF, EGFR, CASP3, AKT1, MAPK1, MAPK3, mTOR, and IL-6) followed the human cytomegalovirus infection." (PMID 36817449, 2023). "Other similar GE interplay are those of FK Binding Protein Prolyl Isomerase 5 (FKBP5) and childhood trauma, AKT-8 retrovirus Serine/Threonine Kinase 1 (AKT1) and cannabis use, and Catenin Alpha 3 (CTNNA3) and cytomegalovirus infection in utero." (PMID 34829493, 2021).
glaucoma (10 papers, 2019 to 2025). Increased pressure in the eyeball due to obstruction of the outflow of aqueous humor. "In this study, AKT1, predicted to be the most critical target gene for EB treatment of glaucoma, was subjected to molecular docking validation with its binding chemical components." (PMID 40826712, 2025). "CytoHubba and molecular docking results further suggest AKT1’s significant involvement in EB’s therapeutic effects on glaucoma." (PMID 40826712, 2025). "Intriguingly, the results of this work have shed new light on the possible remarkable roles of AKT1, CXCL12, and HRAS genes in the pathogenesis of glaucoma." (PMID 36973823, 2023).
influenza (10 papers, 2019 to 2026). An acute viral infection of the respiratory tract, occurring in isolated cases, in epidemics, or in pandemics; it is caused by serologically different strains of viruses (influenzaviruses) designated A, B, and C, has a 3-day incubation period, and usually lasts for 3 to 10 days. "In summary, through an in silico study, we identified AKT1 as a potential target and the PI3K/AKT pathway as possibly the main pathway associated with curcumin’s action against influenza." (PMID 34577580, 2021). "In influenza, hypercapnia (HC) is a risk factor for mortality in patients with severe acute and chronic lung diseases, suppressing macrophage antiviral activity and increasing mortality of influenza A infection via AKT1." (PMID 34803696, 2021). "Network pharmacology identified genistein and daidzein as key bioactive constituents targeting hub proteins TNF, AKT1, EGFR, SRC, and MMP9, which mediate pathological process in influenza." (PMID 41957261, 2026). "Overall, these reports support our pathway (PI3K/AKT) and target (AKT1) results for curcumin and influenza, as well as our in vitro study of prophylactic and therapeutic effects of curcumin and AKT target confirmation." (PMID 34577580, 2021). "A. paniculata may exert therapeutic effects against influenza by acting on core targets, such as TNF, IL‐6, AKT1, GAPDH, and STAT3." (PMID 41439108, 2025). "A. paniculata may exert its therapeutic effects against influenza by modulating core targets such as TNF, IL‐6, AKT1, GAPDH, and STAT3." (PMID 41439108, 2025).
insomnia (10 papers, 2022 to 2026). A sleep disorder characterized by difficulty in falling asleep and/or remaining asleep. "AKT1 is directly related to insomnia via correction of sleep–wake disturbances, while ALB indirectly reflects sleep status through its level fluctuations." (PMID 41367024, 2025).